WEE1 (WEE1 G2 checkpoint kinase)
Diseases named in the same sentence as WEE1 in open-access papers (continued):
Sharing a sentence is not in itself a finding about the gene and the disease.
osteosarcoma (24 papers, 2011 to 2026). A usually aggressive malignant bone-forming mesenchymal neoplasm, predominantly affecting adolescents and young adults. "Downregulation of miR‐15b‐associated Wee1 expression may participate in the drug resistance in osteosarcoma." (PMID 28145098, 2017). "MK-1775, a specific Wee1 inhibitor, has been tested as a possible therapeutic option in sarcomas; e.g., Wee1 inhibition has been shown to sensitize osteosarcoma cells in vitro to chemotherapy or radiation at clinically feasible concentrations." (PMID 31015476, 2019). "We found that anti-tumoral activity of gemcitabine and the Wee1 kinase inhibitor AZD1775 in osteosarcoma cells, was dependent on drug sequencing that relied on p27 stabilization." (PMID 30992462, 2019). "We further examined the expression of miR‐15b and Wee1 in a tissue microarray (TMA) panel of clinical osteosarcoma samples." (PMID 28145098, 2017). "The resulting correlation coefficient and P‐value of r = −0.28 and P < 0.005 indicated that miR‐15b expression was weakly but inversely correlated with Wee1 expression in osteosarcoma tissues." (PMID 28145098, 2017). "The results showed that miR‐15b expression was inversely correlated with Wee1 expression; expression of miR‐15b was lower in osteosarcoma tissues and was coupled with high expression of Wee1." (PMID 28145098, 2017). "We further analysed the correlation between Wee1 expression and the prognosis of patients with osteosarcoma in the osteosarcoma TMA samples." (PMID 28145098, 2017). "In total, 27 frozen osteosarcoma samples with miR‐15b expression were evaluated against Wee1 expression from matched TMA samples for this analysis." (PMID 28145098, 2017). "In other cell types including HeLa and osteosarcoma, checkpoint abrogation by inhibition of WEE1 results in extensive mitotic catastrophe." (PMID 26025928, 2015). "Similarly to RAP2C, the role of WEE1 in Osteosarcoma has been researched and mentioned as a therapeutic target." (PMID 39869252, 2025). "As miR‐15b and its targeted genes, including Wee1 and Bcl‐2, hold great potential for the treatment of chemoresistance, this research provides strong evidence for future development of miR‐based therapeutics strategies directed at treating osteosarcoma." (PMID 28145098, 2017). "Wee1 inhibition has also been shown to sensitize osteosarcoma to radiotherapy." (PMID 28145098, 2017). "Similar results have also been obtained using siRNA against Wee1 in human osteosarcoma cells." (PMID 28978051, 2017). "We hypothesized that direct inhibition of the Wee1 pathway in osteosarcoma cells may lower the apoptotic threshold and increase chemotherapy sensitivity." (PMID 28145098, 2017). "Ectopic expression of miR‐15b in osteosarcoma MDR cells reduced the expression of Wee1, which may contribute to drug resistance." (PMID 28145098, 2017). "We verified that miR‐15b expression negatively correlated with Wee1 levels in osteosarcoma cells." (PMID 28145098, 2017). "The discrepancy between miR‐15b and Wee1 expression for clinical prognosis in osteosarcoma may relate to multiple potential target genes of miR‐15b." (PMID 28145098, 2017). "We determined the correlation between expression of miR‐15b and Wee1 in osteosarcoma tissues." (PMID 28145098, 2017). "Because miR‐15b inversely regulates Wee1 expression, we also evaluated whether downregulation of miR‐15b in osteosarcoma samples was correlated with Wee1 upregulation." (PMID 28145098, 2017). "We applied both in vitro and in vivo experimental and clinical findings to observe that miR‐15b is reduced in drug‐resistant osteosarcoma cells and tissues, which affected the chemosensitivity of osteosarcoma cells maybe partly through the regulation of Wee1." (PMID 28145098, 2017).
osteosarcoma (continued). "However, the association and biological functions of miR‐15b and Wee1 have not yet been investigated in osteosarcoma." (PMID 28145098, 2017). "In fact, in the U2OS osteosarcoma cells, the inhibition of DDK reduced the level of apoptosis induced by the WEE1 inhibitor alone, suggesting a potential antagonistic relationship within these cells." (PMID 36338546, 2022). "Wee1 inhibition by a small molecule compound, PD0166285 in MG-63, U2OS, and Saos-2 osteosarcoma cell lines resulted in their sensitization to irradiation-induced cell death." (PMID 34503094, 2021). "Another Wee1 inhibitor, MK-1775, enhanced the cytotoxic effect of gemcitabine in MG63, A673, U2OS, and HT-1080 osteosarcoma cell lines, OS-patient tumor explants, and a patient-derived mouse xenograft model." (PMID 34503094, 2021). "We found that Wee1 is a target gene of miR‐15b and observed that transfection with miR‐15b inhibits Wee1 expression and partially reverses MDR in osteosarcoma cell lines." (PMID 28145098, 2017). "Subsequently, we evaluated the mechanisms of the deregulation of expression of the most significantly altered miR (miR‐15b) in osteosarcoma MDR cell lines and identified Wee1 as a miR‐15b‐targeted gene." (PMID 28145098, 2017). "We next addressed the effects of combined Wee1 and Chk1 inhibition in U2OS osteosarcoma cells." (PMID 28030798, 2017). "In accordance with these results, inhibition of Wee1 (PD0166285) did not induce cell cycle arrest or cell death when used as mono-treatment in a study with osteosarcoma cell lines." (PMID 23767999, 2013). "To ascertain that WEE1 inhibition does not radiosensitize normal cells, we compared cell viability of human primary osteoblasts to osteosarcoma cell lines after 4 Gy irradiation, in the presence or absence of 0.5 μM PD0166285." (PMID 21529352, 2011).
Alzheimer disease (23 papers, 2011 to 2025). A progressive, neurodegenerative disease characterized by loss of function and death of nerve cells in several areas of the brain leading to loss of cognitive function such as memory and language. "Wee1, a mitotic regulator, was found to be upregulated in the brains of patients with Alzheimer’s disease." (PMID 38338859, 2024). "Half of the identified genes exhibit no direct or indirect association to HD, although the genes FLJ10761, WEE1 and PI3K had previously been linked to neurodegeneration in Alzheimer's disease and lipid metabolism that was reported to be affected in HD." (PMID 22162763, 2011). "WEE1 and FLJ10761 were reported to be associated with Alzheimer's disease." (PMID 22162763, 2011).
chronic myeloid leukemia (20 papers, 2000 to 2025). "Our data demonstrated that Wee1 participated in promoting cell proliferation and imatinib resistance in chronic myeloid leukemia via regulating DNA damage repair dependent on ATM-γH2AX-MDC1." (PMID 36575478, 2022). "Combining the WEE1 inhibitor MK‐1775 with vitamin K2 enhanced cytotoxicity and apoptosis in Chronic myeloid leukemia(CML) cells, including TKI‐resistant strains." (PMID 40893386, 2025).
sarcoma (20 papers, 2013 to 2026). A usually aggressive malignant neoplasm of the soft tissue or bone. "To identify additional drug susceptibilities in HRDhigh sarcoma based on their genomic instability traits, we focused on the WEE1 protein, which belongs to the serine/threonine family of protein kinases." (PMID 36779660, 2023). "Recently, we found that CIC::DUX4 sarcoma cells tolerate a high replicative stress state through an increased dependence on the G2/M checkpoint kinase, WEE1, which delays mitotic entry to enable DNA repair prior to mitosis." (PMID 40760094, 2025). "To analyze the effect of WEE1 inhibition on sarcoma cell viability, we subjected five HRDhigh and five HRDlow patient-derived ex vivo sarcoma cell models to the WEE1 inhibitor (WEE1i) adavosertib." (PMID 39535612, 2024). "We evaluated PARP1/2 and WEE1 inhibition ex vivo in patient-derived sarcoma cell models as monotherapy and in combination with chemotherapeutic agents to identify synergistic effects." (PMID 39535612, 2024). "Recent studies have shown CDK4/6 inhibitors such as palbociclib, which can make sarcoma cells sensitive to Wee1 kinase inhibition through reversible cell cycle arrest." (PMID 37089080, 2023). "To investigate the effect of WEE1 inhibition in HRDhigh sarcoma, we performed a six‐point dose–response curve with the WEE1 inhibitor adavosertib in our ex vivo patient‐derived sarcoma models." (PMID 36779660, 2023). "The sarcoma cell lines U2-OS was selected for the proteome studies as it has been well characterized for WEE1 functions, notably, adavosertib and more prolonged WEE1 siRNA treatment yielded comparable results." (PMID 36632060, 2023). "Our HRDhigh sarcoma cell models also showed high sensitivity to WEE1 inhibition, a tyrosine kinase involved in G2 checkpoint signaling." (PMID 36779660, 2023). "Through this analysis, we identified a WEE1-mediated adaptive response that enables CIC-DUX4 sarcoma survival by limiting massive DNA damage and mitotic catastrophe." (PMID 35315355, 2022). "Through our studies we provide the initial translational framework for use of WEE1 inhibition as a therapeutic strategy in CIC-DUX4 sarcomas." (PMID 35315355, 2022). "Through an integrative transcriptional and functional approach, we investigated how CIC-DUX4 sarcomas survive in a CCNE1-mediated high-replication-stress state through increased dependence on the WEE1 kinase." (PMID 35315355, 2022). "Coupled with the enhanced caspase-3/7 activity observed upon adavosertib treatment, these findings indicate that pharmacologic inhibition of WEE1 induces apoptosis in CIC-DUX4 sarcoma cells, potentially through increased DNA damage and premature mitotic death." (PMID 35315355, 2022). "Specifically, CIC-DUX4 sarcomas depended on WEE1 activity to limit DNA damage and unscheduled mitotic entry." (PMID 35315355, 2022). "One barrier in exploring the clinical response to WEE1 inhibitors in CIC-DUX4 patients is the relative rarity of CIC-DUX4 sarcomas." (PMID 35315355, 2022). "Through an integrative transcriptional and kinase activity screen using patient-derived specimens, we now show that CIC-DUX4 sarcomas depend on the G2/M checkpoint regulator WEE1 as part of an adaptive survival mechanism." (PMID 35315355, 2022). "These in vivo studies further validated WEE1 as a therapeutic vulnerability in CIC-DUX4 sarcomas that can be readily targeted through clinically advanced WEE1 inhibitors, including adavosertib." (PMID 35315355, 2022). "For example, MK1775, a small selective kinase inhibitor compound of WEE1, induces unscheduled mitotic entry and apoptosis in sarcoma cells." (PMID 34298017, 2021). "Wee1 can be targeted with the small molecule MK-1775, which showed in vitro activity against a variety of sarcoma cell lines." (PMID 26322224, 2015).
sarcoma (continued). "Thus, similar to other cancers, WEE1 expression in CIC::DUX4 sarcoma provides a molecular break that delays cell-cycle progression under high replicative stress states to enable effective DNA repair prior to mitosis." (PMID 40760094, 2025). "In order to prevent the accumulation of DNA damage in S phase and to subsequently prevent premature mitotic entry, CIC::DUX4 sarcomas depend on the G2/M checkpoint kinase WEE1 to delay mitotic entry and to ensure proper DNA repair and integrity prior to mitosis." (PMID 38882060, 2024). "Consequently, genetic or pharmacologic WEE1 inhibition in vitro and in vivo led to rapid DNA damage–associated apoptotic induction of patient-derived CIC-DUX4 sarcomas." (PMID 35315355, 2022). "Thus, we identified WEE1 as a vulnerability targetable by therapeutic intervention in CIC-DUX4 sarcomas." (PMID 35315355, 2022). "Thus, we next tested the translational impact of targeting the WEE1 kinase in preclinical models of CIC-DUX4 sarcoma." (PMID 35315355, 2022). "Moreover, we demonstrate that WEE1 is a therapeutic vulnerability in CIC-DUX4 sarcomas that can be targeted with clinically advanced WEE1 inhibitors." (PMID 35315355, 2022). "Thus, we demonstrate that CIC-DUX4 sarcomas transcriptionally upregulate CCNE1, compromising the G1/S checkpoint and conferring dependence on WEE1 to limit DNA damage–associated cell death." (PMID 35315355, 2022). "In addition, as part of a mechanism of adaptation to CCNE1 upregulation, and the subsequent DNA damage and unscheduled mitotic entry, CIC–DUX4 sarcoma cells become particularly dependent on the G2/M cell cycle checkpoint WEE1." (PMID 36358827, 2022). "Similarly, ZN-c3 (WEE1 inhibitor; Zentalis) is entering phase II studies as monotherapy and/or combination therapy in solid tumors, including sarcomas." (PMID 35315355, 2022). "Since CIC-DUX4 transcriptionally upregulates CCNE1, which can induce a high-replicative-stress state in cancer, we hypothesized that WEE1 activity in CIC-DUX4 sarcomas may be an adaptive survival mechanism." (PMID 35315355, 2022). "MK-1775 is a Wee1-kinase inhibitor which has been used for blocking of sarcoma growth." (PMID 31015476, 2019). "Similarly, sarcoma cells were shown to be more sensitive to agents active in S-G2 phase, such as doxorubicin and Wee1 kinase inhibitors, after palbociclib pre-treatment." (PMID 31506466, 2019). "Wee1 inhibition is also effective in patient‐derived sarcoma cells; MK1775 as a single agent causes significant apoptotic cell death, suggesting that Wee1 inhibition may represent a novel approach in the treatment of sarcomas." (PMID 28145098, 2017). "ETCTN participating sites throughout the United States can collaborate to conduct early trials that target CIC-rearranged sarcoma with NCI-IND agents, such as WEE1 inhibitors." (PMID 38882060, 2024). "Mirroring MNK1/2 silencing, ETC-168 treatment strongly blocks eIF4E phosphorylation and represses expression of sarcoma-driving onco-proteins including E2F1, FOXM1, and WEE1." (PMID 33564073, 2021). "Since WEE1 inhibition with adavosertib induces premature mitotic entry and DNA damage in other cancer types, we next determined the effect of adavosertib on cell cycle progression in our patient-derived CIC-DUX4 sarcoma cells." (PMID 35315355, 2022). "For example, inhibition of Wee1 by the selective small‐molecule inhibitor MK1775 can abrogate the G2‐M checkpoint, resulting in premature mitotic entry and initiation of apoptotic cell death in all sarcoma cells tested." (PMID 28145098, 2017).
sarcoma (continued). "Since CCNE1 expression is a clinically validated biomarker of WEE1 inhibitor response, we anticipate that individuals with CIC-DUX4 sarcomas, but not other small round blue cell tumors including ES or alveolar rhabdomyosarcoma, will benefit from WEE1 inhibitor treatment." (PMID 35315355, 2022).
neuroblastoma (19 papers, 2011 to 2025). Neuroblastoma (NB) is the most common solid, extracranial childhood tumor. "As direct target, the key cell cycle regulator WEE1 has been identified in neuroblastoma, again associated with impaired survival in miR-497 down-regulated samples." (PMID 26251897, 2015). "The synergistic enhancement of CDDP induced apoptosis through miRNA or siRNA mediated WEE1 inhibition indicates a potential therapeutic strategy for high risk neuroblastoma." (PMID 23531080, 2013). "WEE1, a tyrosine kinase regulator of the cell cycle and predicted target of miR-497, has emerged as an oncogene in several cancer types and therefore represents an attractive potential target for novel therapy approaches in high-risk neuroblastoma." (PMID 23531080, 2013). "We also found that CHD5 represses transcription of WEE1, in both neuroblastoma and pancreatic cancer cell lines." (PMID 25247294, 2014). "We determined that miR-497 directly targets and inhibits WEE1 protein expression in neuroblastoma cell lines, resulting in increased apoptosis." (PMID 23531080, 2013). "Given that siRNA mediated inhibition of WEE1, a now validated target of miR-497, had a similar phenotypic effect on our neuroblastoma cell lines, Annexin V/PI assays were performed using siWEE1." (PMID 23531080, 2013). "We have identified a novel target of miR-497, WEE1 tyrosine kinase, an emerging novel therapy target and potent pro-survival protein in neuroblastoma." (PMID 23531080, 2013). "Interestingly, simultaneous pharmacologic inhibition of CHEK1 and WEE1, both miR-497 targets, acted synergistically to impair neuroblastoma cell growth in vitro and in vivo, further demonstrating the therapeutic potential of miR-497." (PMID 26824183, 2016). "We identified WEE1 as a novel target for miR-497 in neuroblastoma." (PMID 23531080, 2013). "Furthermore, our analysis showed that high WEE1 levels are significantly associated with poor EFS and OS in neuroblastoma and that siRNA knockdown of WEE1 in MNA cell lines results in significant levels of apoptosis, supporting an oncogenic role of WEE1 in neuroblastoma." (PMID 23531080, 2013). "In neuroblastoma, LINC01410 enhances the expression of WEE1 by acting as a sponge for miR-506-3p, thereby promoting the progression of the cell cycle." (PMID 41472748, 2025). "WEE1, CHEK1, BRCA1, FANCD2, PARP1, and phosphorylation of CHEK1 and ATR were significantly reduced in TRPM2 deleted neuroblastoma and myeloid leukemia cells after doxorubicin treatment." (PMID 35428820, 2022). "Several cell cycle regulators, such as PLK1, TRIM16, WEE1, CDK4/6, and CCND1, have been shown to be involved in the tumorigenesis of neuroblastoma." (PMID 26225123, 2015).
bladder cancer (18 papers, 2015 to 2024). "An additional gene implicated in human bladder cancer, the tumor suppressor WEE1, is located in the disease associated chr21:31405230-33951574 region." (PMID 38778091, 2024). "Treatment with nimbolide decreased the protein levels of Cdc25c, Cdc2, and cyclin B1 and increased the expression of Wee1 and p21WAF1 in bladder cancer cells." (PMID 31391858, 2019). "In the current study, exposure of bladder cancer cells to isorhamnetin markedly reduced the expression of cyclin B1 and Wee1, without significant changes in the expression of Cdk1." (PMID 31590241, 2019).